USP22 (ubiquitin specific peptidase 22)
Diseases named in the same sentence as USP22 in open-access papers (continued):
Sharing a sentence is not in itself a finding about the gene and the disease.
cancer (continued). "Ubiquitin-specific protease 22 (USP22), a deubiquitinating enzyme, is a therapeutic target in cancer patients." (PMID 34502538, 2021). "Thus, the development of new cancer therapies targeting USP22 may yield promising results." (PMID 32616828, 2020). "Our findings suggest USP22 plays critical roles in the malignancy and progression of NSCLC and provide rationales for targeting USP22, which induces broad anti-cancer activities, as a novel therapeutic strategy for NSCLC patient." (PMID 31842906, 2019). "However, studies to date also suggest USP22 may function as a tumor suppressor in cancers." (PMID 31842906, 2019). "By the RNAseq analysis, we found that USP22 knockout significantly suppressed angiogenesis and EMT signaling pathways that play essential roles in cancer growth and metastasis." (PMID 31842906, 2019). "The effects of USP22 knockout on sensitivity to cisplatin and irradiation, and growth, metastasis of NSCLC xenografts, and survival of cancer-bearing mice were investigated." (PMID 31842906, 2019). "Therefore targeting USP22 may sensitize cancer cells to irradiation and cisplatin treatment." (PMID 31842906, 2019). "The ubiquitin-specific protease 22 (USP22) is an oncogene and its expression isupregulated in many types of cancer." (PMID 30088609, 2018). "USP22 is a subunit of the human SAGA (hSAGA) transcriptional regulation complex and contributes to cancer ‘stemness’ by activating a range of genes." (PMID 28881649, 2017). "IHC revealed that USP22 and AP4 were concurrently overexpressed in distant metastases, particularly in liver metastasis lesions, compared with corresponding primary carcinoma in CRC patients." (PMID 28427243, 2017). "This review will focus on USP22, which has recently emerged as an important DUB that leads to cancer progression in several types of cancer." (PMID 27057639, 2016). "USP22 regulates CCNB1 protein stability to promote cell cycle progression, as well as cancer cell growth, when it is aberrantly upregulated." (PMID 27030811, 2015). "Ubiquitin-specific peptidase 22 (USP22) is a member of the ubiquitin-specific processing proteases (USPs) and is recognized as a biomarker for predicting tumor metastasis and recurrence due to its overexpression in malignant tumors." (PMID 40183543, 2025). "In this study, we identified USP22, an oncogene involved in promoting cancer cell growth and tumor immune evasion, as a negative regulator of MHC-I expression across a variety of human and mouse cancer cell lines." (PMID 41252204, 2025). "Therapeutic strategies could focus on creating modulators to enhance or mimic ALKBH5 activity, targeting the overexpression of USP22 and RNF40, offering a new potential treatment for cancers with m6A abnormalities." (PMID 39048965, 2024). "In addition, USP22, and USP9X stabilize PD-L1 through deubiquitination, promoting cancer development and migration." (PMID 39048965, 2024). "Moreover, in the current work, we identified an important role of USP22 in promoting the mitochondrial biogenesis transcriptomic program, further strengthening the essential function of this DUB in the energy supply of cancer cells." (PMID 38347585, 2024). "Taken together, our findings demonstrate that USP7 inhibition can dramatically upregulate USP22 in cancer cells; and targeting USP7 and USP22 may represent a more effective approach for targeted cancer therapy, which warrants further study." (PMID 37946202, 2023).
cancer (continued). "Lastly, both USP7 and USP22 are involved in immunosuppression through stabilizing immune check-point inhibitor PD-L1 in cancer and FOXP3 in Tregs, and the significance of this feedback deserves to further study using immune-component cancer model." (PMID 37946202, 2023). "The USP22 has been studied in cancer for more than 15 years, but inhibitors of USP22 have not been reported until recent studies." (PMID 35924159, 2022). "In addition, USP22, EGFR, MET and MAPK were reported to act as targets of miR-30e-5p in human cancers." (PMID 34998399, 2022). "The widely accepted finding of USP22 overexpression in cancer by immunohistochemistry (IHC) analysis is not consistent with the results of several additional genome-wide studies." (PMID 36123698, 2022). "Besides OTUB1, other DUBs, such as USPs family (USP1, USP7, USP8, USP15, USP22), OTUs family (OTUD7B, OTUD6B, A20, and OTUB2) and other DUBs have been identified to regulate the progression of various cancers and applied for clinical cancer therapy." (PMID 35715413, 2022). "Additionally, USP22 participates in cell cycle regulation and apoptosis by deubiquitinating Cyclin D122, Cyclin B123, and SIRT124 in cancer cell proliferation." (PMID 35449157, 2022). "We further demonstrate that USP22 is a CIN gene, indicating that USP22 deletions, which are frequent in many tumor types, may drive genetic heterogeneity and contribute to cancer pathogenesis." (PMID 33801331, 2021). "In addition, another study has identified that USP22 is a major effector of AR levels, AR output, AR-MYC coordination, and the transition to CRPC to drive a lethal cancer progression." (PMID 34548474, 2021). "The expression of USP22 increases with the progression of oral carcinogenesis from non-cancerous mucosa to primary carcinoma and from carcinomas to lymph node metastasis." (PMID 34070986, 2021). "In detail, USP22 expression is increased in parallel with the progression of oral carcinogenesis, from non-cancerous mucosa to primary carcinoma and from carcinomas to lymph node metastasis." (PMID 32560247, 2020). "Furthermore, we also found that USP22 knockout drastically suppressed activation of AKT, ERK signaling pathways in both A549 and H1299 cancer cells." (PMID 31842906, 2019). "To explore the significance of USP22 expression in NSCLC tissues, we first examined USP22 protein in 202 cancer tissues and their matched noncancerous lung tissues by immunohistochemical analysis." (PMID 31842906, 2019). "In addition to USP22, USP7 and 12 have also been reported to be more highly expressed in PCa compared to non-cancer tissue by IHC20,22." (PMID 30177856, 2018). "Although collectively, the IHC-based studies detailed above suggest that USP22 is predominantly overexpressed in cancer, the technical limitations of the approaches employed do not preclude diminished USP22 expression from also contributing to oncogenesis." (PMID 29210986, 2017). "DUBs are critical key players in diverse processes such as (i) spermatogenesis (e.g. USP2, USP8, USP9y, USP14, USP26, Uchl-1, Uchl-3 and CYLD), (ii) cancer biology (e.g. USP7, USP10 and USP11), and (iii) stemness and differentiation (e.g. USP7, USP9x, USP22, USP44 and Psmd14)." (PMID 28659380, 2017). "Remarkably, diminished expression of USP22 and/or overexpression of RNF20/40 at the mRNA level is observed in 38% of primary tumors in colorectal adenocarcinoma, a cancer type characterized by a very high prevalence of chromosome instability (up to 85% of cases)." (PMID 29210986, 2017). "Although DNA/RNA sequencing and IHC studies provide insight into USP22 expression in cancer, none are sufficient to accurately evaluate altered USP22 activity." (PMID 29210986, 2017).
cancer (continued). "We detected simultaneous overexpression of USP22 and AP4 in CRC primary carcinoma." (PMID 28427243, 2017). "Our study demonstrates that USP22 is a CCNB1 deubiquitinase, suggesting that targeting USP22 might be an effective approach to treat cancers with elevated CCNB1 expression." (PMID 27030811, 2015). "Based on our discovery, it will not be surprising to add USP22 in the list of the abnormally upregulated APC/C targets in human cancers." (PMID 27030811, 2015). "In the present study, we detected USP22 expression in HCC cell lines and cancer tissues." (PMID 25909224, 2015). "Interestingly, upregulation of USP22 accompanies with the regulation of the BMI-1 pathway and c-Myc pathway in ACC-83 cancer cell lines." (PMID 24466336, 2014). "Moreover, USP22 acts as an oncogene by regulation the BMI-1 pathway and c-Myc pathway in ACC-83 cancer cell lines." (PMID 24466336, 2014). "In order to further support the expression of USP22 in SACC, we further analyzed the expression of USP22 in freshly frozen SACC cancer tissues and matched adjacent noncancerous tissues from 20 SACC tumor patients using western blot analysis." (PMID 24466336, 2014). "The USP22 expression increased significantly from non-cancerous mucosa to carcinomas (P<0.001) and from carcinomas to lymph node metastasis (P<0.001)." (PMID 22880026, 2012). "Finally, while 15 DUBs were found to be significantly dysregulated in only one type of cancer, 7 (UCHL1, USP9X, USP11, USP10, USP22, COPS5 and COPS6) displayed multiple alterations in two or more tumor types." (PMID 21283576, 2011). "How USP22 impacts cancer development and progression, however, is still not well defined." (PMID 38236941, 2024). "Therefore, the p-MYH9 /USP22/HIF-1α axis is critical for LR and cancer stemness." (PMID 39300073, 2024). "In all cases, the functions of USP22 in cancer may reflect its activity towards histone substrates and gene regulation or to removal of ubiquitin from non-histone substrates by USP22 that may impact other processes, such as telomere stability or DNA repair." (PMID 38236941, 2024). "Therefore, USP22 and CSN5 work together to stable PD-L1 expression in cancer cells." (PMID 37658402, 2023). "Moreover, overexpression of USP22 alone was not sufficient to drive tumor formation in mice but disrupted several cancer‐related pathways." (PMID 38045832, 2023). "On the other hand, several ubiquitin-specific peptidases, including USP7, USP22, OTUB1, and CSN5, regulate PD-L1 protein expression in an opposing fashion through removal of the polyubiquitin modification from PD-L1 and consequently protect PD-L1 from proteasomal degradation in cancer cells." (PMID 38038129, 2023). "In addition, USP22 is involved in regulating the function of multiple non-histone targets, which are correlated with cancer progression and poor prognosis." (PMID 35784926, 2022). "Notably, overexpression of AP2 also significantly enhanced the proliferation of USP22-WT H1299 and A549, but not in USP22-KO H1299 and A549 cancer cells." (PMID 36123698, 2022). "Thus, the USP22-FASN axis revealed in this study may be a critical mechanism for the maintenance of CSC properties and therapy resistance of human cancer, which deserves further investigation." (PMID 36333288, 2022). "This may have broader relevance to situations where USP22, but not other members of SAGA, is associated with human disease states, particularly where cell polarity is frequently disrupted, such as cancer." (PMID 33988679, 2021). "In addition to its links with H2Bub1, USP22 also has non-histone substrates with important links to cancer." (PMID 33233707, 2020). "Additionally, the USP22 nuclear immunostaining was only found in the parent cancer cell xenografts but not in USP22−/− cancer cell xenografts and adjacent normal cells and tissues." (PMID 31842906, 2019). "However, there is no information on the genome-wide binding sitesof USP22 and its direct target genes in cancer cells." (PMID 30088609, 2018).
cancer (continued). "However, the role of Usp22 overexpression in cancer etiology is not known." (PMID 34503086, 2021). "The Ubiquitin Specific Peptidase 22 (USP22), a component of the Spt-Ada-Gcn5 Acetyltransferase (SAGA) histone modifying complex, is overexpressed in multiple human cancers, but how USP22 impacts tumorigenesis is not clear." (PMID 38236941, 2024). "We demonstrate that USP22 and AP4 are simultaneously overexpressed in primary carcinoma compared with their non-cancerous mucosa and are both up-regulated in EMT in CRC cells." (PMID 28427243, 2017).
tumor (137 papers, 2011 to 2026). "USP22 stabilizes PD-L1 by removing K48-linked ubiquitin chains, sustaining its expression on the tumor cell surface and dampening CD8+ T cell-mediated cytotoxicity." (PMID 41359051, 2025). "The increased tumor suppression by Usp22 deletion is associated with increased tumor cell surface H-2Kb and β2M expression, the elevated tumoral-infiltrating CD8+ T cells and their production granzyme B, IFN-γ, and TNF-α." (PMID 41252204, 2025). "Here, we identify USP22 as novel regulator of basal and tumor-associated PML and PML-RARα function, interferon (IFN) regulation and APL differentiation." (PMID 38467608, 2024). "It was recently reported that the significant reduction in tumor volume/weight upon stable knockdown of USP22 in B16 is associated with a decrease in PD-L1 stability." (PMID 35884430, 2022). "In contrast, USP22 can exert tumor‐suppressive functions in CRC, such that its loss increases CRC burden by modulating mTOR activity." (PMID 34743406, 2022). "To test if the higher levels of ATF3 and the impaired tumor phenotype upon loss of USP22 in HER2+-BC are caused by sustained activation of the UPR, we analyzed several known markers and genes regulated by this pathway." (PMID 34007022, 2021). "By contrast, USP22-associated ubiquitination dysregulation has been implicated in many diseases including tumours." (PMID 34226501, 2021). "Consistently, loss of USP22 renders tumor cells more sensitive to apoptosis and significantly increases the efficiency of therapies targeting the ER folding capacity." (PMID 34007022, 2021). "The underpinning protumourigenic USP22 on tumour cells was EMT induction, exhibiting loss of epithelial E-cadherin and gain of mesenchymal vimentin, with upregulation of MMP2/9 invasive markers in CCA cell lines." (PMID 34226501, 2021). "Further analyses demonstrated that Usp22 loss not only delayed tumor growth but also strongly reduced tumor burden as reflected by the decreased number of tumors per animal and slower tumor growth kinetics." (PMID 34007022, 2021). "In an earlier study, we identified USP22 as a tumor suppressor in CRC since the loss of Usp22 resulted in severe tumor burden in mice." (PMID 33920268, 2021). "USP22 protein was highly expressed in tumor tissues of LUAD patients, which was associated with a short survival time meanwhile." (PMID 32294625, 2020). "One such study showed that intestine specific USP22 deletion impaired the tumor phenotype associated with Apc mutation and positively correlated with the intestinal tumor burden and decreased survival." (PMID 34660907, 2020). "Our previous studies have confirmed that defects in USP22 can not only cause cell cycle arrest in G0/G1 phase, but also inhibit apoptosis and promote tumor cell proliferation." (PMID 32294625, 2020). "We found that upregulation of USP22 was well associated with tumor outgrowth, extracapsular invasion, clinical stages, and poor prognosis of ATC." (PMID 27145278, 2016). "High USP22 expression was also associated with shortened survival time in patients at advanced tumor stages and with high grade HCC." (PMID 25909224, 2015). "Correlation analysis further demonstrated that high USP22 expression was associated with clinical stage and tumor grade in HCC." (PMID 25909224, 2015). "Therefore, USP22-mediated MHC-I suppression appears to be a critical mechanism underlying tumor evasion of CD8+ T cell immunity in a variety of human cell types." (PMID 41252204, 2025). "On the other hand, PML expression is reduced in many tumor types, favoring pro-tumorigenic effects of USP22 on cell cycle progression, but it remains unclear how USP22 regulates the tumor-associated functions of PML." (PMID 38467608, 2024). "Notably, the intestine-specific deletion of Usp22 in a genetic mouse model for adenomatous polyposis coli (APC)-associated CRC exacerbated the tumor phenotype, thereby confirming the context-dependent tumor-suppressive function of USP22." (PMID 33920268, 2021).